MGAT1 (alpha-1,3-mannosyl-glycoprotein 2-beta-N-acetylglucosaminyltransferase)
Diseases named in the same sentence as MGAT1 in open-access papers (continued):
Sharing a sentence is not in itself a finding about the gene and the disease.
MGAT1 also shares sentences with these, for which no sentence is quoted: colon carcinoma (2 papers); osteosarcoma (2); alcoholic (1); Allergy (1); Anxiety (1); cervical cancer (1); colorectal carcinoma (1); diabetes (1); glioblastoma (1); Glucose intolerance (1); Hyperinsulinemia (1); Insulin resistance (1); neurodevelopmental disorder (1); nonalcoholic fatty liver disease (1); pancreatic ductal adenocarcinoma (1); pancreatic insufficiency (1); premature ovarian insufficiency (1); respiratory tract tumor (1); steatosis (1); type 2 diabetes (1); viral infection (1); Wilms tumor (1).